ZNF649 (zinc finger protein 649)
Description:
Transcriptional repressor. Regulator of transcriptional factor complexes and may suppress SRE and AP-1 transcription activities mediated by growth factor signaling pathways.
Synonyms: FLJ12644
Tractability: PROTAC: UniProt records ubiquitination sites on it.
Gene: Protein-coding gene on chromosome 19 (51,889,233 to 51,905,049, reverse strand). Ensembl gene ENSG00000198093.
Subcellular location: Nucleus
Pathways (Reactome):
Gene expression (Transcription): Generic Transcription Pathway; Regulation of endogenous retroelements by KRAB-ZFP proteins
Gene Ontology:
Molecular function: protein binding; DNA-binding transcription factor activity; RNA polymerase II cis-regulatory region sequence-specific DNA binding
Biological process: regulation of transcription by RNA polymerase II; regulation of DNA-templated transcription
Cellular component: extracellular region; nucleus
Genetic constraint (gnomAD): Loss-of-function variants: 5 observed, 12.92 expected, observed/expected ratio (o/e) 0.39, 90% interval 0.2 to 0.81. The upper end of that interval is the gene's LOEUF score, 0.81, which puts it in group 3 of 6, group 1 being the genes least tolerant of losing a copy. Missense variants: 531 observed, 627.66 expected, observed/expected ratio (o/e) 0.85, 90% interval 0.79 to 0.91. Synonymous variants: 223 observed, 218.69 expected, observed/expected ratio (o/e) 1.02, 90% interval 0.91 to 1.14.
Homologues: Orthologues: chimpanzee ZNF649 (99% identical), pig ZNF649 (60% identical), tropical clawed frog MGC115716 (11% identical), Drosophila melanogaster CG14442 (6% identical), Drosophila melanogaster CG14440 (4% identical). Paralogues in human: ZNF613 (64% identical), ZNF350 (58% identical), ZNF567 (45% identical), ZNF382 (40% identical), ZNF564 (34% identical), IKZF1 (17% identical), IKZF3 (15% identical), IKZF4 (15% identical), ZNF639 (15% identical), IKZF2 (15% identical), ZNF821 (12% identical).
Diseases named in the same sentence as ZNF649 in open-access papers:
ZNF649 is named in the same sentence as 3 diseases in open-access papers, as found by Europe PMC text mining. Sharing a sentence is not in itself a finding about the gene and the disease. The quoted sentences say what the papers report.
prostate tumors (1 paper, 2012). "A similar fusion event between ZNF649 and ZNF577 was identified in prostate tumors." (PMID 22720068, 2012).
cancer (2 papers, 2022). A tumor composed of atypical neoplastic, often pleomorphic cells that invade other tissues. "Several genes from the zinc finger family, including ZNF577, ZNF649, ZNF615, ZNF614, and ZNF432, are under intense investigation due to their altered methylation status in various cancer types." (PMID 36553064, 2022).
ZNF649 also shares sentences with these, for which no sentence is quoted: multiple sclerosis (1 paper).